TNIK (TRAF2 and NCK interacting kinase)
Diseases named in the same sentence as TNIK in open-access papers (continued):
Sharing a sentence is not in itself a finding about the gene and the disease.
multiple myeloma (3 papers, 2017 to 2025). "Here, we investigated the relationship between interleukin-6-induced proliferation of multiple myeloma cells and Traf2- and Nck-interacting kinase (TNIK) expression in Wnt signaling." (PMID 28467797, 2017). "Interleukin-6 increased the proliferation of multiple myeloma cells and TNIK mRNA and protein expression." (PMID 28467797, 2017). "Others have reported that IL6 promoted the interaction of the TNIK/β-catenin/TCF4 complex (multiple myeloma cells:); transcriptional activity of the β-catenin/TCF4 complex is promoted by TNIK and inhibited by SF1, which induces an alternative splicing activity." (PMID 40003000, 2025). "In addition, we examined the effect on TNIK of TNIK inhibitor KY-05009 and receptor tyrosine kinase inhibitor dovitinib and whether inhibition of TNIK suppresses the interleukin-6-induced proliferation of multiple myeloma cells." (PMID 28467797, 2017). "Our results provide crucial information that TNIK is involved in the interleukin-6-dependent proliferation of multiple myeloma cells and inhibition of Wnt signaling involving TNIK could be a therapeutic strategy for the treatment of interleukin-6-dependent multiple myeloma." (PMID 28467797, 2017).
prostate carcinoma (3 papers, 2022 to 2024). A carcinoma that arises from epithelial cells of the prostate gland. "To test the efficacy of NCB-0846 during prostate cancer treatment and in CRPC, we initially assessed the efficacy of NCB-0846 in suppressing TNIK protein expression in C4-2 and PC3 cells." (PMID 38226156, 2024).
atherosclerosis (2 papers, 2023 to 2025). A disease characterized by the build-up of fatty material and calcium deposition in the arterial wall resulting in partial or complete occlusion of the arterial lumen. "We here investigate the role of TNIK-deficient B cells in atherosclerosis." (PMID 37215541, 2023). "To determine the role of B cell TNIK in atherosclerosis, we generated ApoE−/−TNIKfl/fl (TNIKBWT) and ApoE−/−TNIKfl/fl CD19-cre (TNIKBKO) mice, which were fed a high cholesterol diet for 10 weeks." (PMID 37215541, 2023). "In the current paper, we investigated the role of B cell specific TRAF2- and NCK-interacting kinase (TNIK) in atherosclerosis." (PMID 37215541, 2023). "We here conclude that in hyperlipidemic ApoE−/− mice, B cell specific TNIK deficiency does not affect atherosclerosis." (PMID 37215541, 2023). "Although our data do not show any effect of B cell TNIK deficiency on atherosclerosis, B cell TNIK may play an important role in IgA mediated diseases." (PMID 37215541, 2023). "Interestingly, when we analyzed atherosclerosis in B cell TNIK deficient atherosclerotic mice, we did not observe any effects on plaque size or composition, with the exception of a trend towards a decrease in plaque macrophage content." (PMID 37215541, 2023). "However, this TNIK-deficiency induced increase in mucosal IgA did not affect atherosclerosis in our model." (PMID 37215541, 2023). "As TNIK seems to be involved in the CD40-TRAF6 signaling complex, and as B cell CD40 activation seems to accelerate atherosclerosis, we here aimed to elucidate the role of TNIK signaling in B cells in atherosclerosis." (PMID 37215541, 2023). "A plausible mechanistic model may involve TNIK interaction with MAGI1, a PDZ domain–containing scaffold protein previously shown to regulate ER stress signaling and atherosclerosis in ECs." (PMID 40672381, 2025). "We conclude that TNIK signaling in B cells does not affect atherogenesis, nor did it affect immunological pathways relevant for atherosclerosis." (PMID 37215541, 2023). "In conclusion, TNIK signaling in B cells does not play a role in the pathogenesis of atherosclerosis." (PMID 37215541, 2023).
leukemia (2 papers, 2017 to 2020). A malignant (clonal) hematologic disorder, involving hematopoietic stem cells and characterized by the presence of primitive or atypical myeloid or lymphoid cells in the bone marrow and the blood. "The importance of the CD27/TNIK/Wnt signaling pathway has been documented before in leukemia stem cells." (PMID 32242021, 2020). "We recently showed that TNIK signaling favors symmetric (SD) over asymmetric (AD) cell division in leukemia stem cells." (PMID 32242021, 2020). "Similarly, TNIK signaling induces proliferation and self-renewal of leukemia stem cells." (PMID 32242021, 2020). "Although the biological function of TNIK in hematological cancers, such as MM and leukemia, has not been clearly investigated yet, our results suggest a new approach for treating MM stimulated by exogenous IL-6." (PMID 28467797, 2017).
non-small cell lung carcinoma (2 papers, 2016 to 2020). A group of at least three distinct histological types of lung cancer, including non-small cell squamous cell carcinoma, adenocarcinoma, and large cell carcinoma. "We recently revealed that a small-molecule Traf2 and Nck-interacting kinase (TNIK) inhibitor, NCB-0846,30 suppressed the EMT and metastasis of non-small cell lung cancer cells through post-translational modification of actinin-4 (unpublished observation)." (PMID 32265507, 2020).
Obesity (2 papers, 2021 to 2022). Accumulation of substantial excess body fat. "RAP2A can also activate atypical MAPKs, such as TNIK, MINK, and MAP4K4, stimulating JNK and other downstream kinases, suggesting that RAP2A may have functions beyond desensitization of the β3-AR in healthy adipocytes and in the context of obesity." (PMID 34847077, 2022).
psychosis (2 papers, 2023). "TNIK is up-regulated by either Apoer2-ICD, which provides another mechanism by which reduced Reelin signaling could impart risk for psychosis." (PMID 37461529, 2023).
type 2 diabetes (2 papers, 2013 to 2023). "TNIK has also been reported as a susceptibility locus associated with type 2 diabetes." (PMID 37311878, 2023).
viral infection (2 papers, 2020 to 2023). "The downregulation of IFN signaling resulting from TNIK depletion may ultimately increase susceptibility to virus infection." (PMID 38264262, 2023). "Our findings suggest that TNIK plays a crucial role in regulating the EC response to virus infections through modulation of the IFN pathway." (PMID 38264262, 2023). "To understand how virus infection affects TNIK protein expression, we conducted experiments in HUVECs." (PMID 38264262, 2023). "Here the authors show upon acute viral infection TNIK is critically required as a regulator of effector and memory T cell differentiation." (PMID 32242021, 2020). "To evaluate the role of TNIK in CD8+ T cells during an acute viral infection in vivo, we generated a tamoxifen inducible TnikF/F;UBC-Cre+ mouse." (PMID 32242021, 2020).
ankylosing spondylitis (1 paper, 2023). An autoimmune chronic inflammatory disorder characterized by inflammation in the vertebral joints of the spine and sacroiliac joints. "This is unexpected, as TNIK plays a role key role in Wnt signaling, a pathway with a role in several immune related diseases such as Rheumatoid Arthritis and Ankylosing Spondylitis." (PMID 37215541, 2023).
attention deficit hyperactive disorder (1 paper, 2024). "Patients with the homozygous TNIK pArg180* (R180X) mutation show no TNIK protein and have been diagnosed with recessive IDD, delayed speech, and attention deficit hyperactive disorder (ADHD)." (PMID 38638602, 2024).
B cell deficiency (1 paper, 2023). A broad classification of disorders where circulating numbers of B lymphocytes are decreased or ineffective. "In addition, stem cells and mature immune cells present in the bone marrow were unaffected by B-cell deficiency of TNIK." (PMID 37215541, 2023).
benign prostatic hyperplasia (1 paper, 2024). A non-cancerous nodular enlargement of the prostate gland. "We observed elevated expression levels of TNIK not only in CR-LNCaP tumors in mice but also in CRPC patients compared with those with localized PCa and benign prostatic hyperplasia (BPH)." (PMID 38226156, 2024).
cardiomyopathy (1 paper, 2013). A disease of the heart muscle or myocardium proper. "From these tables, we found that gene clusters anchored by the major genes CGREF1, PMS1 and TNIK all had multiple genes in several cardiomyopathy-related pathways." (PMID 23879630, 2013).
cognitive decline (1 paper, 2021). "This timing of the cognitive decline is consistent with our study design wherein we identified methylation changes in ASH1L and TNIK after 1 week of high-altitude exposure." (PMID 34262470, 2021).
colorectal tumor (1 paper, 2020). "TNIK is a vital regulatory factor of Wnt signaling,and colorectal tumor cells are extremely based on the expression and catalytic activity of TNIK for proliferation." (PMID 32831519, 2020).
epilepsy (1 paper, 2024). A brain disorder characterized by episodes of abnormally increased neuronal discharge resulting in transient episodes of sensory or motor neurological dysfunction, or psychic dysfunction. "Nevertheless, in this study, TNIK biology facilitated our understanding of the submolecular dysfunction underlying epilepsy." (PMID 38292191, 2024). "We found that TNIK was primarily located in neurons and decreased significantly in epilepsy model rats and TLE patients compared with controls." (PMID 38292191, 2024). "We found that TNIK was down-regulated in epilepsy, and the inhibition of TNIK using NCB-0846 alleviated seizure activity." (PMID 38292191, 2024). "Further analyses of interacting proteins should aid in elucidating the biological functions of TNIK in the progression of epilepsy." (PMID 38292191, 2024). "A pentylenetetrazole (PTZ)-induced epilepsy rat model was used to determine the effect of the TNIK inhibitor NCB-0846 on behavioral manifestations of epilepsy." (PMID 38292191, 2024). "In addition, we also tested the expression of TNIK in the acute phase of epilepsy in a pilocarpine-induced epilepsy rat model." (PMID 38292191, 2024). "Although our results thus far indicate the participation of TNIK activity in seizure behavioral and molecular abnormalities, the mechanism of constitutive TNIK signaling in epilepsy should be investigated further in the future using genetic knockout or overexpression of TNIK." (PMID 38292191, 2024). "In this study, we hypothesized the involvement of TNIK in epilepsy and investigated TNIK expression in patients with intractable TLE and in a pilocarpine-induced rat model of epilepsy by western blotting, immunofluorescence, and immunohistochemistry." (PMID 38292191, 2024). "Traf2-and NcK-interacting kinase (TNIK) has recently attracted attention as a critical modulation target of many neurological and psychiatric disorders, but its role in epilepsy remains unclear." (PMID 38292191, 2024). "To test our hypothesis, we evaluated the expression pattern of TNIK in the brains of TLE patients and epileptic rat models and tested the effect of the TNIK inhibitor NCB-0846 in a pentylenetetrazole (PTZ)-induced rat model of epilepsy." (PMID 38292191, 2024). "Moreover, our immunohistochemical data showed that TNIK is weaker in samples with epilepsy than in the controls, whether in patients or in rats." (PMID 38292191, 2024). "This expression pattern and previous data might imply TNIK's important role in epilepsy." (PMID 38292191, 2024). "Together, these data showed that TNIK might be an important factor involved in epilepsy." (PMID 38292191, 2024). "TNIK down-regulation might be an endogenous protection mechanism for TLE patients, and its agonists or overexpression might be deleterious to epilepsy patients." (PMID 38292191, 2024). "Moreover, TNIK expression is significantly down-regulated in TLE patients, which provides evidence that TNIK might be involved in epilepsy." (PMID 38292191, 2024).
helminth infections (1 paper, 2022). "To test the efficacy of TNIK inhibition in these models, we focused on two prototypical inhibitors: NCB0846 (NCB), which has been tested preclinically and mebendazole (MBZ), which is approved by the FDA for treatment of helminth infections." (PMID 35675910, 2022).
Kawasaki disease (1 paper, 2023). A rare inflammatory disease characterized by an acute febrile, systemic, self-limiting, medium-vessel vasculitis primarily affecting children. "Additionally, in a gene expression study involving patients with Kawasaki disease, a systemic vasculitis syndrome of unknown etiology, TNIK was identified as one of the major dysregulated genes." (PMID 38264262, 2023). "Thus, our findings regarding the role of TNIK in IFN regulation may hold crucial implications for understanding and managing systemic inflammatory diseases that significantly affect the vasculatures, such as Lupus Erythematosus and Kawasaki disease." (PMID 38264262, 2023).
lung squamous cell carcinoma (1 paper, 2023). "Recently, a study has shown that TNIK (MAP4K7) phosphorylates NF2 at S13 and promotes tumorigenesis in lung squamous cell carcinoma (LSCC)." (PMID 36929007, 2023).
lymph node metastasis (1 paper, 2015). "In the multivariate analysis, high TNIK expression, lymph node metastasis, and advanced age were identified as independent factors associated with worse RFS." (PMID 26499327, 2015). "With respect to OS, univariate analysis indicated that advanced age, female gender, poorly differentiated histology, T4, lymphatic invasion, venous invasion, lymph node metastasis, elevated CEA level, and high TNIK expression were significantly associated with worse OS." (PMID 26499327, 2015). "In the univariate analysis, advanced age (≥70 years), poorly differentiated histology, T4, lymphatic invasion, venous invasion, lymph node metastasis, elevated carcinoembryonic antigen (CEA) level, and high TNIK expression were significantly associated with worse RFS." (PMID 26499327, 2015).
muscle atrophy (1 paper, 2025). The loss of muscle tissue due to inactivity or disease. "In addition to lung, TNIK is extensively expressed in the heart, brain, and skeletal muscle, suggesting dysfunction of TNIK may contribute to age-related diseases in these organs, such as cardiovascular diseases, neurodegenerative disease, and muscle atrophy." (PMID 39965245, 2025).
non-small cell lung adenocarcinoma (1 paper, 2020). Type of epithelial lung cancer arising from glandular origin. "Although the association of TNIK with EMT in non-small cell lung adenocarcinoma has not been fully studied in many reports, inhibition of metastasis and invasion through TNIK inhibition is expected to play a role in increasing the therapeutic effect." (PMID 32810161, 2020).
osteoporosis (1 paper, 2024). A condition of reduced bone mass, with decreased cortical thickness and a decrease in the number and size of the trabeculae of cancellous bone (but normal chemical composition), resulting in increased fracture incidence. "Ultimately, we identified potential targets indicating that TNIK downregulation affects the adverse effect of RPD on osteoporosis." (PMID 39268461, 2024).
protein deficiency (1 paper, 2024). "However, the role of mutations found in patients with TNIK protein deficiency and the lack of TNIK protein kinase activity during early stages of neuronal and synapse development has not been characterized." (PMID 38638602, 2024).
retinoblastoma (1 paper, 2018). A malignant tumor that originates in the nuclear layer of the retina. "Based on these results, TNIK can be considered as a potential therapeutic target for retinoblastoma." (PMID 29914080, 2018). "Stress response proteins that were identified to be hyperphosphorylated in retinoblastoma compared to control retina tissues included H2AFX, SIRT1, TNIK, WRNIP1, BAZ1B, and CDK1." (PMID 29914080, 2018).
sarcoma (1 paper, 2021). A usually aggressive malignant neoplasm of the soft tissue or bone. "Together, our findings support the feasibility of TNIK as the first molecular target for OS treatment and may be of great value for further clinical development of targeted Wnt signaling in OS and multiple subtypes of sarcoma." (PMID 33400690, 2021).
synovial sarcoma (1 paper, 2020). "This study revealed for the first time the therapeutic potential of TNIK inhibition in synovial sarcoma." (PMID 32429395, 2020). "Synovial sarcoma is highly dependent upon the expression of TNIK for cell proliferation and survival, and a small-molecule TNIK inhibitor NCB-0846 induced rapid apoptotic death of synovial sarcoma cells." (PMID 32429395, 2020). "In conclusion, we demonstrated for the first time that TNIK is a feasible drug target in synovial sarcoma." (PMID 32429395, 2020). "The four synovial sarcoma cell lines were transfected with siRNA to TNIK (siTNIK#2) or control siRNA (siCtrl), and their viability was assessed 72 h later." (PMID 32429395, 2020). "Using immunohistochemistry, the expression of β-catenin and TNIK was then examined in tissue specimens resected from 20 patients with synovial sarcoma." (PMID 32429395, 2020). "This study demonstrated for the first time the therapeutic potential of TNIK inhibition in synovial sarcoma." (PMID 32429395, 2020). "Nuclear expression of TNIK was detected in all four cell lines examined (green), and TNIK was co-localized with β-catenin in the nuclei of synovial sarcoma cell lines with Wnt activation (merge)." (PMID 32429395, 2020). "In the present study, we revealed that Wnt signaling is activated in synovial sarcoma cells and that siRNA-mediated or pharmacological TNIK inhibition reduced their viability and induced apoptosis." (PMID 32429395, 2020). "Based on the remarkable growth suppression and apoptosis induction in synovial sarcoma cells by silencing of the TNIK gene, the sensitivity of synovial sarcoma cell lines to a small-molecule TNIK inhibitor, NCB-0846, was then evaluated." (PMID 32429395, 2020). "Here, we report the therapeutic potential of TNIK inhibition in synovial sarcoma." (PMID 32429395, 2020). "Based on these findings, we speculated that TNIK inhibition would be effective for treatment of synovial sarcoma." (PMID 32429395, 2020). "Transfection of three siRNA constructs targeting TNIK (siTNIK#1, #2, and #3) into HS-SY-II and SYO-1 synovial sarcoma cells was confirmed to reduce the levels of TNIK gene expression relative to cells transfected with control siRNA (Ctrl)." (PMID 32429395, 2020). "We examined the efficacy of a small interfering RNA (siRNA) to TNIK and a small-molecule TNIK inhibitor, NCB-0846, for synovial sarcoma." (PMID 32429395, 2020).